FECH (ferrochelatase)
Diseases named in the same sentence as FECH in open-access papers (continued):
Sharing a sentence is not in itself a finding about the gene and the disease.
neovascular age-related macular degeneration (2 papers, 2020 to 2023). "Interestingly, endothelial FECH is upregulated in experimental models of human ocular neovascularization diseases as neovascular age-related macular degeneration (AMD) and retinopathy of prematurity (ROP)." (PMID 36631598, 2023). "In addition, FECH was overexpressed in and around these lesions, and in human wet age-related macular degeneration eyes." (PMID 32760270, 2020).
Acute hepatic porphyria (1 paper, 2022). Acute hepatic porphyrias represent a sub-group of porphyrias (see this term) characterized by the occurrence of neuro-visceral attacks with or without cutaneous manifestations. "Furthermore, the method can be used to monitor the in vivo expression patterns in patients under mRNA altering therapies like gene specific silencing RNAs (for example givosiran against ALAS1 in the acute hepatic porphyrias) or splice modulating oligos directed against FECH c.[315-48C]." (PMID 35923227, 2022).
brain tumors (1 paper, 2021). "For example, it has been suggested that ABCG2, FECH, and HO‐1 could serve as indicators of treatment outcome for ALA-PDT of brain tumors, while in HNC, STAT3 could be used as a molecular marker of cumulative photoreaction therapy monitoring." (PMID 34302323, 2021).
breast carcinoma (1 paper, 2021). "The repression of oncogenic Ras/MEK signaling pathway reduced the activity of FECH and increased PpIX accumulation, which blocked breast cancer progression both in vitro and in vivo." (PMID 34553073, 2021).
chronic myeloid leukemia (1 paper, 2024). "We modified chronic myeloid leukemia K562 cells with CRISPR/Cas9-mediated KO of the genes encoding FECH and ALAS2." (PMID 38649187, 2024).
desmoid tumor (1 paper, 2016). A desmoid tumor (DT) is a benign, locally invasive soft tissue tumor associated with a high recurrence rate but with no metastatic potential. "Overexpression of ferrochelatase was found in more aggressive forms of desmoid tumors and was associated with a poor clinical outcome." (PMID 27564260, 2016). "Furthermore, a recent gene expression profiling linked the outcome of patients with desmoid tumors with the ferrochelatase expression." (PMID 27564260, 2016).
edema (1 paper, 2022). An abnormal accumulation of fluid beneath the skin, or in one or more cavities of the body. "Hence, ferrochelatase, a catalyst that inserts zinc into protoporphyrin, may be beneficial for reducing brain edema." (PMID 35603937, 2022).
esophageal tumor (1 paper, 2015). "Because increased PBGD activity and decreased FECH activity were detected in some esophageal tumor cells/tissues, the ratio of PBGD to FECH activity was proposed as an index to predict enhanced PpIX accumulation and cell sensitivity to ALA-PDT." (PMID 26516850, 2015).
gastrointestinal carcinomas (1 paper, 2021). "In previous studies, we were able to demonstrate a significant down regulation of FECH in gastrointestinal carcinomas leading to the accumulation of PpIX within the tumor cells." (PMID 34461853, 2021). "In previous studies, we found a significant down regulation of the relevant enzyme ferrochelatase in gastrointestinal carcinomas leading to an accumulation of protoporphyrin-IX within the tumor cells." (PMID 34461853, 2021).
graft versus host disease (1 paper, 2021). An immune system disorder that occurs after allogeneic hematopoietic stem cell transplant and is a reaction of donor immune cells against host tissues. "Genes in the high-expression cohorts of FECH, GYPA, RPIA, and XK were highly enriched in ribosome, graft versus host disease, primary immunodeficiency, and B cell receptor signaling pathways, respectively." (PMID 34861826, 2021).
hereditary hemochromatosis (1 paper, 2025). An inherited metabolic disorder characterized by iron accumulation in the tissues. "Genetic testing revealed a heterozygous mutation in the FECH gene in the EPP case and an HFE gene mutation in a PCT case with hereditary hemochromatosis." (PMID 40510110, 2025).
hypochromic anemia (1 paper, 2023). Anemia caused by the reduction of hemoglobin in relation to the red cell volume. "It inactivates δ-ALAD and ferrochelatase (thus inhibiting heme biosynthesis and causing hypochromic anemia), and reduces the activity of the most important antioxidant enzymes: superoxide dismutase (SOD), catalase (CAT), and glutathione peroxidase (GPX)." (PMID 37048229, 2023).
iron overload (1 paper, 2022). "Although high levels of PPIX accumulate because of reduced FECH activity, no signs of iron overload are found in patients with EPP." (PMID 35309058, 2022).
malignant lymphoma (1 paper, 2022). "The accumulation of PpIX in malignant lymphoma cell lines may be due to increased activity of porphobilinogen deaminase, an enzyme that metabolizes 5-ALA, and decreased activity of ferrochelatase, an enzyme that binds PpIX to iron ions." (PMID 35203195, 2022).
metastasis (1 paper, 2016). The spread or migration of cancer cells from one part of the body (where they first appeared) to another. "A heterogeneous downregulation of the ferrochelatase in different patients and even within an individual metastasis might be responsible for a heterogeneous 5-ALA-induced fluorescence behavior of cerebral metastases." (PMID 27564260, 2016).
photosensitivity (1 paper, 2022). "For example, ferrochelatase deficit-accumulating free PpIX in the skin leads to photosensitivity, as well as gain of function of 5-ALA synthase 2 (ALAS2) leading to accumulation of PpIX-Zinc and photodermatosis." (PMID 36077783, 2022).
prostate tumor (1 paper, 2019). "Similar to FECH, CROT does not consistently differentially express between the primary prostate tumor and normal prostate." (PMID 31295943, 2019).
Pythiosis (1 paper, 2015). A granulomatous disease caused by the aquatic organism PYTHIUM insidiosum and occurring primarily in horses, cattle, dogs, cats, fishes, and rarely in humans. "The predisposition of thalassemic, iron overloaded patients to pythiosis, the observation of iron deficiency anemia in rabbits experimentally infected with P. insidiosum and the report of a functional ferrochelatase gene in P. insidiosum has elicited interest in the role of iron in pythiosis." (PMID 25738758, 2015).
renal carcinoma (1 paper, 2025). A carcinoma arising from the epithelium of the renal parenchyma or the renal pelvis. "SETD2 modulates FECH expression via H3K36me3-mediated transcriptional regulation, influencing ferroptosis sensitivity in renal cancer cells." (PMID 41203594, 2025).
Stroke (1 paper, 2023). Sudden impairment of blood flow to a part of the brain due to occlusion or rupture of an artery to the brain. "Based on the role of metabolism in stroke, we extracted seven genes related to the “porphyrin metabolism” and “glycine, serine and threonine metabolism” pathways, including ALAS2, FECH, COX10, GCAT, HMBS, PGAM2, and AOC2." (PMID 36968495, 2023).
vulvar cancer (1 paper, 2022). "In our studies, the resistance to PDT in vulvar cancer cell lines developed as a result of changes in the amount of heme metabolism enzymes (PPOX, FECH) that led to decreased amount of PpIX, changes in the number of mitochondria and cellular metabolism, as well as ROS and antioxidant capacity." (PMID 36499013, 2022).
tumor (48 papers, 1998 to 2025). "Next, analysis of the ChIP-seq database (ENCODE) showed that H3K36me3 was enriched at the FECH promoter region in a variety of tumor cell lines." (PMID 37604811, 2023). "PpIX accumulates in tumor cells due to the increased activity of enzymes in the initial stage of heme synthesis in tumor cells, as well as a deficiency in ferrochelatase, an enzyme that utilizes PpIX by converting it into heme." (PMID 35200407, 2022). "However, in tumor cells, which are deficient in ferrochelatase, the administration of exogenous 5-ALA leads to the accumulation of PpIX." (PMID 39518115, 2024). "Our data indicate that KDM4C and GATA1 cooperate to upregulate FECH, the terminal enzyme in heme biosynthesis, enhancing mitochondrial bioenergetics, oxidative phosphorylation, and supporting tumor aggression." (PMID 40259045, 2025). "Our study addresses this gap by examining how the interaction between KDM4C and GATA1 collaboratively regulates FECH expression, providing new insights into the molecular mechanisms linking heme metabolism to tumor growth and aggressiveness." (PMID 40259045, 2025). "Overall, the enhanced fluorescence is associated with low expression of ferrochelatase, overexpression of ABCB6, low expression of ABCG2, the accumulation of heme synthesis-related metabolites caused by IDH1 mutations, and the tumor microenvironment." (PMID 39518115, 2024). "The weight and volume of tumor in the combined si-FECH and erastin treatment group were also smaller than that in the erastin alone group." (PMID 37604811, 2023). "It has also been recently reported that inhibition of FECH directly promotes ferroptosis in tumor cells." (PMID 37604811, 2023). "Exogenous administration of ALA-5 leads to a tumor entity-independent protoporphyrie-IX accumulation in tumor cells due to a missing or downregulated ferrochelatase activity in tumors." (PMID 38146509, 2023). "Our results indicate that AV25R binds with several proteins known to regulate cell proliferation and tumor progression, such as FECH, MAP11, EGFR, TGFBR1 and MDM2." (PMID 38138609, 2023). "The FECH mRNA expression in ccRCC primary tumor specimens was remarkably attenuated in contrast with those in normal tissues (P < 0.001)." (PMID 36059798, 2022). "The proportion of FECH expression in tumor specimens was measured with the aid of the Z-score criterion, and the ccRCC cohort was then classified into low- and high-expression groups premised on the levels of FECH expression." (PMID 36059798, 2022). "This was because MEK contributes to increased expression of ABCB1, a drug efflux transporter that releases PpIX from tumor cells, and to the activity of ferrochelatase, which converts PpIX to heme." (PMID 35203195, 2022). "Gene ontology (GO) analysis, and gene set enrichment analysis (GSEA) were conducted based on TCGA data, and a single-sample GSEA was utilized to explore the link between FECH expression and the infiltration status of immune cells in the tumor." (PMID 36059798, 2022). "It was suggested that one of the reasons for preferential PpIX accumulation was lower activity of ferrochelatase in tumor cells, compared to that in normal cells." (PMID 34439326, 2021). "If PpIX, the photo- and sono-dynamically active compound of 5-ALA, is known to accumulate in HGGs due to abnormal ferrochelatase activity in glial cells, its selectivity for these other tumor types is expected to be much less pronounced." (PMID 34235081, 2021). "In tumor cells, ferrochelatase activity is lower compared to normal tissue, and thus, PpIX accumulates mostly in tumor cells." (PMID 30519770, 2019). "In tumor cells the synthesis of PpIX is highly activated and ferrochelatase mRNA expression is down-regulated so PpIX tends to accumulate specifically in tumor tissues." (PMID 30134852, 2018). "Two genes, MAFG and FECH were significantly upregulated in five and four tumour types, respectively, in the presence of NFE2L2 aberrations (FDR<0.1)." (PMID 26436532, 2015).
tumor (continued). "In previous studies, the activity of ferrochelatase was found to be the key factor in tumor-selective PpIX accumulation." (PMID 25822972, 2015). "PPIX is an intermediate by-product in the heme biosynthetic pathway and it preferentially accumulates in tumor cells due to changes in the activity of two main enzymes, porphobilinogen deaminase and ferrochelatase." (PMID 24310585, 2011). "ALA-PDT does exhibit a degree of intrinsic tumour selectivity owing to differing tumour levels of enzymes in the haem pathway (e.g. ferrochelatase) leading to higher tumour PpIX levels." (PMID 19240715, 2009). "The indiscriminate fluorescence regardless of histopathology in meningiomas has been attributed to high protein expression of PpIX metabolism genes including ABCB6, ABCG2, CPOX, and FECH throughout all tumor grades, which enables high-throughput metabolism and accumulation." (PMID 40282508, 2025). "HGG cells lack ferrochelatase, leading to PpIX accumulation and tumor-specific fluorescence." (PMID 41282203, 2025). "Thus, PpIX accumulates more in tumor cells than in healthy cells due to decreased ferrochelatase activity." (PMID 39001362, 2024). "FECH expression was also correlated with many features of tumor progression, including histological grade, clinical TNM stage, and invasion depth (T stage), which implied that, similar to SETD2, low expression of FECH was associated with high histological grade, clinical TNM stage, and T stage." (PMID 37604811, 2023). "In normal cells, the final product of this metabolic pathway is heme protein, while in tumor cells, protoporphyrin IX (PpIX) is the main product that accumulates inside mitochondria because of the downregulation of ferrochelatase (the enzyme that converts PpIX into heme)." (PMID 35624942, 2022). "Thus, reduced FECH expression can lead to PpIX accumulation in tumor cells under treatment with exogenous 5-ALA." (PMID 36059798, 2022). "Similar studies on the silencing of the FECH gene were also conducted on other neoplasms." (PMID 35055109, 2022). "In addition, the RAS/MEK pathway increased PpIX accumulation in cancer cells by regulating the FECH activity mechanism, which would facilitate precise recognition of tumor boundaries and small satellite tumors." (PMID 36059798, 2022). "The aim of this study was to find out whether pretreatment of tumor cells with Alectinib leads to an enhanced concentration of PpIX due to inhibition of FECH and how this affects the induction of cell death." (PMID 34461853, 2021). "Therefore, a lower level of ferrochelatase cannot convert PpIX to heme, which results in the excessive accumulation of PpIX within tumor cells." (PMID 34439326, 2021). "Ferrochelatase mRNA expression levels strongly negatively correlated with PpIX accumulation, representing the first report of a correlation between mRNA expression related to PpIX accumulation and PpIX concentration in canine tumor cells." (PMID 30959982, 2019). "These enzymes are highly expressed in many tumours, with complex roles in cancer progression, but whether PpIX accumulates because FECH activity is inhibited by higher levels of NO in cancer has yet to be fully explored." (PMID 31406300, 2019). "Increased permeability of blood brain barrier, increased uptake of PpIX by adenosine triphosphate (ATP)-binding cassette B6, reduction of ferrochelatase levels, increased metabolism of malignant tumor cells, elevated cellular density, neoangiogenesis in areas of malignancy have all been implicated." (PMID 29414911, 2018). "As expected, most tumor samples displayed expression of ABCB6, ABCG2, FECH and CPOX in our study, and expression was strongly correlated with fluorescence." (PMID 36612300, 2023). "We studied the expression of proteins that possibly affect ALA-mediated PpIX accumulation, namely oligopeptide transporter-1 and -2, ferrochelatase and ATP-binding cassette transporter G2 (ABCG2), in several tumor cell lines." (PMID 23189181, 2012).
tumor (continued). "Because the expression levels of ABCG2, PEPT1, PEPT2 and ferrochelatase (FECH) are important factors that affect ALA-mediated PpIX accumulation, expression of these proteins were measured in several tumor cell lines by Western blotting analysis." (PMID 23189181, 2012). "However, in tumor cells like HGG, FECH activity and intracellular concentration of ferrous iron (Fe2+) are significantly reduced, which leads to the intracellular accumulation of PpIX." (PMID 40282508, 2025). "Similar to SETD2 knockdown, FECH knockdown did not have a significant effect on cell activity, however, siFECH can increase the sensitivity of erastin to tumor cells." (PMID 37604811, 2023). "A compound of this pharmacologic agent accumulates predominately in tumor cells due to a lack of reduced ferrochelatase activity and becomes visible under blue light filters." (PMID 34733239, 2021). "The limited capacity of ferrochelatase (FECH) and increased enzymatic activity of ALA dehydratase (ALAD), porphobilinogen deaminase (PBGD) and uroporphyrinogen decarboxylase (UROD) result in the accumulation of exogenous PpIX in tumor cells." (PMID 33171665, 2020). "The amount of PpIX in tumor cells is favored by both the activity of cytosolic porphobilinogen deaminase (PBGD) during the replication phase, and by the down-regulation of ferrochelatase (FECH)." (PMID 31380388, 2019). "As an initial approach to optimize delta-aminolaevulinic acid (delta-ALA)-induced photosensitization of tumours, we examined the response of three enzymes of the haem biosynthetic pathway: delta-ALA dehydratase, porphobilinogen deaminase (PBGD) and ferrochelatase." (PMID 9460994, 1998). "In view of safety of patients, it is important that the excessive accumulation of PpIX in mitochondria is tumour-specific because ferrochelatase is inactive in tumour cells owing to the lack of electron supply from the tricarboxylic acid cycle due to the Warburg effect." (PMID 35365766, 2022). "While, this observation seems paradoxical from a fluorescence standpoint, a complete upregulation of the heme biosynthesis pathway makes sense from a tumor biological point of view, since FECH rather than the intermediate metabolite PpIX is required for several cellular processes." (PMID 35665365, 2022). "Similarly, FECH does not significantly change between normal and primary tumor based on the TCGA dataset." (PMID 31295943, 2019). "The expression level of FECH and CROT is not significantly changed between normal and primary tumor based on the MSKCC dataset." (PMID 31295943, 2019). "Notably, unspecific low-to-moderate expression of ABCB6 (median score 8, range: 8–9), ABCG2 (median score 3, range: 1–4), FECH (median score 4, range: 1–8) and CPOX (median score: 1, range: 0–1) was also found in all nine fluorescent cortex samples lacking tumor invasion." (PMID 36612300, 2023). "Although we did not assess the effects of ferrochelatase, we suggested that the increased cellular PpIX level may be at least partly attributable to the uptake of 5-ALA into brain or GSCs through down-regulation of MDR-1 by celecoxib, thereby enhancing anti-tumor effects." (PMID 34301977, 2021).